ABCB11 (ATP binding cassette subfamily B member 11)
Diseases named in the same sentence as ABCB11 in open-access papers (continued):
Sharing a sentence is not in itself a finding about the gene and the disease.
fibrosis (2 papers, 2012 to 2022). the formation of excess fibrous connective tissue in an organ or tissue in a reparative or reactive process. "Fibrosis progression has been associated with variants of Vitamin D receptor (VDR) and ABCB11 (bile salt export pump)." (PMID 23342360, 2012).
Hepatitis C (2 papers, 2012 to 2022). "The aim of this study was to investigate a possible association of ABCB11 c.1331 T > C with hepatitis C virus (HCV) infection and fibrosis stages as assessed by non-invasive transient elastography in a German cohort of patients." (PMID 22681771, 2012).
primary biliary cholangitis (2 papers, 2014 to 2025). Primary biliary cholangitis (PBC) is a chronic and slowly progressive cholestatic liver disease of autoimmune etiology characterized by injury of the intrahepatic bile ducts that may eventually lead to liver failure. "It has been described to cause altered splicing events of ABCB11 through severe exon skipping in vitro and possibly associates with primary biliary cirrhosis (PBC)." (PMID 24969679, 2014).
progressive familial intrahepatic cholestasis type 3 (2 papers, 2014 to 2025). Progressive familial intrahepatic cholestasis type 3 (PFIC3), a type of progressive familial intrahepatic cholestasis (PFIC), is a late-onset hereditary disorder in bile formation that is hepatocellular in origin. "Rare genetic hepatobiliary diseases, such as PFIC2 (ABCB11/BSEP deficiency) and progressive familial intrahepatic cholestasis type 3 (PFIC3) (ABCB4/MDR3 deficiency) highlight the importance of apposite BA handling in maintaining both liver and biliary health." (PMID 40513781, 2025).
Sepsis (2 papers, 2012 to 2024). Sepsis is defined as life-threatening organ dysfunction caused by a dysregulated host response to infection. "Sepsis was also associated with decreased mRNA abundance of hepatic Abcg5/g8 expression (the canalicular cholesterol transporter) and down regulation of the bile acid transporter Abcb11." (PMID 23145105, 2012).
type 2 diabetes (2 papers, 2017 to 2021). "We show that the known loci for HbA1c, such as ABCB11, and the established type 2 diabetes loci, IGF2BP2, and ARAP1, could mediate their effect on type 2 diabetes risk by their action on pancreatic beta-cell glucose sensitivity." (PMID 32944759, 2021).
tyrosinemia (2 papers, 2018 to 2024). An autosomal recessive inherited metabolic disorder caused by mutations in the FAH, HPD, and TAT genes. "Cell therapy has been investigated in animal models with various extents of hepatocyte repopulation, including models of PFIC3 (Mdr2 knockout mice), PFIC2 (Abcb11 knockout mice) and hereditary tyrosinemia." (PMID 30367658, 2018).
bile duct cancer (1 paper, 2011). "Bile salt export pump deficiency (BSEP), caused by mutations in ABCB11, has been associated with bile-duct cancer." (PMID 22312493, 2011). "In a study of 82 different ABCB11 mutations in 109 families, 19 of 128 patients (15%) with BSEP mutations developed hepatobiliary mutations, but only 2 of the 19 were bile-duct cancers, the remaining being HCC." (PMID 22312493, 2011).
dysplasia (1 paper, 2022). A usually neoplastic transformation of the cell, associated with altered architectural tissue patterns. "For example, ABCB11 mutations may cause chronic bile-induced inflammation and increase the risk of dysplasia and neoplasia." (PMID 36010647, 2022).
Glycogen storage disease type-III (1 paper, 2025). "Variants in AGL (Glycogen storage disease type-III; GSD3), ABCB4 (Progressive familial intrahepatic cholestasis type-III; PFIC3) and ABCB11 (PFIC2) genes were the most common affecting 19, 14 and 13 children, respectively." (PMID 41165782, 2025).
herpes zoster (1 paper, 2023). A common dermal and neurologic disorder caused by reactivation of the varicella-zoster virus that has remained dormant within dorsal root ganglia, often for decades, after the patient's initial exposure to the virus in the form of varicella (chickenpox). "Our results suggest that this particular SNP in ABCB11 may dominate the estimation of the causal effect of herpes zoster on GBM, which means the selection of SNPs in the GWAS may influence the soundness of the results." (PMID 38053181, 2023).
tuberculosis (1 paper, 2016). A chronic, recurrent infection caused by the bacterium Mycobacterium tuberculosis. "This study suggested that genetic variants of ABCB11 gene might contribute to anti-tuberculosis drug-induced cholestatic liver injury in Chinese patients." (PMID 27293027, 2016).
vitamin deficiency (1 paper, 2016). A disorder that is caused by the deficiency of a vitamin. "However, higher serum BA and more vitamin deficiency were found in patients with ABCB11 deficiency." (PMID 27050426, 2016).
cancer (8 papers, 2015 to 2024). A tumor composed of atypical neoplastic, often pleomorphic cells that invade other tissues. "Interestingly, a case report of HCC in a 17-month-old patient with biallelic germline ABCB11 mutations found somatic mutations in the cancer-related genes beta-catenin (CTNNB1) and nuclear factor erythroid 2-related factor 2 (NFE2L2)." (PMID 36010647, 2022). "The association between ABCB11 mutations and HCC in these patients may relate to chronic cholestasis and inflammation, which provides a milieu for the development of cancer." (PMID 36010647, 2022). "For example, although not a transporter expressed within enterocytes, the activity of the hepatic bile salt export pump (BSEP, encoded by the ABCB11 gene) can be inhibited by several tyrosine kinase inhibitors (TKIs), a class of drugs designed to treat various forms of cancer." (PMID 38675109, 2024). "CBD targets have been suggested to play a role in cancer therapy resistance, including breast cancer resistance protein (ABCG2/BRCP), bile salt export pump (ABCB11/BSEP), and p-glycoprotein (p-gp)." (PMID 36769206, 2023).
tumor (7 papers, 2016 to 2025). "Additionally, hormone deprivation triggered an upregulation of tumor drug resistance genes ABCB11, BIRC3, FGF2 and NRG1." (PMID 40075208, 2025).
gastrointestinal disorders (1 paper, 2016). "The results showed that polymorphisms in rs2287616 had a significant association with increased TBIL, gastrointestinal disorders, arthralgia and itching/rash, indicating the role of genetic variations of ABCB11 in the development of ATDs-induced cholestatic liver injury." (PMID 27293027, 2016).
ABCB11 also shares sentences with these, for which no sentence is quoted: Hyperbilirubinemia (7 papers); Pruritus (7); steatosis (7); genetic disorders (6); cystic fibrosis (5); dyslipidemia (4); Hepatitis (4); Intrahepatic cholestasis of pregnancy (4); BRIC type 1 (3); endotoxemia (3); Hypercholesterolemia (3); hyperlipidemia (3); Tangier disease (3); urea cycle disorder (3); Autoimmunity (2); bile duct obstruction (2); cholestatic jaundice (2); colitis (2); End Stage Liver Disease (2); Failure to thrive (2); inflammation (2); Insulin resistance (2); Jaundice (2); Pseudoxanthoma elasticum (2); acute liver failure (1); acute myeloid leukemia (1); adrenoleukodystrophy (1); alcoholic cirrhosis (1); alcoholic fatty liver disease (1); Ascites (1).
A further 50 diseases each share a sentence with ABCB11 in 1 paper.